UFC1 (ubiquitin-fold modifier conjugating enzyme 1)
Diseases named in the same sentence as UFC1 in open-access papers (continued):
Sharing a sentence is not in itself a finding about the gene and the disease.
tumor (19 papers, 2016 to 2025). "High levels of UFC1 were associated with tumor infiltration." (PMID 34685415, 2021). "Further, sEV-mediated transmission of UFC1 expression was upregulated in tumor serum sEVs from patients with NSCLC and high level of UFC1 were associated with tumor infiltration, while LRG1 is expressed at higher levels in urinary sEVs from patients with NSCLC." (PMID 34685415, 2021). "Moreover, the high-level expression of UFC1 is associated with tumor progression." (PMID 35327612, 2022). "The methylation difference analysis between tumor and normal tissues showed that all 5 gene loci, except UFC1, were hypomethylated." (PMID 38840234, 2024). "LncRNA UFC1 was identified to be overexpressed in HCC tissues, and in vitro and in vivo studies unraveled a tumor-promoting role of UFC1." (PMID 38203767, 2024). "UFC1 expression was upregulated in tumor tissues, serum, and serum exosomes of NSCLC patients and high level of UFC1 was associated with tumor infiltration." (PMID 32242003, 2020). "UFC1 knockdown inhibited NSCLC growth in mouse xenograft tumor models while the simultaneous depletion of PTEN reversed this effect." (PMID 32242003, 2020). "In this study, we found that UFC1 expression level was increased in the tumor tissues, serum and serum exosomes of NSCLC patients." (PMID 32242003, 2020). "We detected the expression of UFC1 in tumor tissues, serum, and serum exosomes of NSCLC patients by qRT-PCR." (PMID 32242003, 2020). "On the contrary, tumor tissues in sh-UFC1 + si-PTEN group had less TUNEL-positive and more Ki-67 positive cells than that in sh-UFC1 alone group." (PMID 32242003, 2020). "The results of immunohistochemical analysis showed that tumor tissues in sh-UFC1 group had more TUNEL-positive and less Ki-67 cells than that in sh-Ctrl group." (PMID 32242003, 2020). "We conducted rescue experiments to determine the importance of Lin28b in UFC1-regulated tumor progression in GC." (PMID 29970131, 2018). "LincRNA-Ubiquitin-Fold Modifier Conjugating Enzyme 1 (lincRNA-UFC1) is also upregulated in HCC tissues and its expression associates with tumor size, stage, and patient outcome." (PMID 29495592, 2018). "In this study, we reported the increased expression of lncRNA UFC1 in tumor tissues, serum and serum exosomes of GC patients." (PMID 29970131, 2018). "The expression level of UFC1 was positively correlated with tumor size, TNM stage and lymphatic metastasis." (PMID 29970131, 2018). "Collectively, we demonstrated that UFC1 was upregulated in tumor tissues, serum, and serum exosomes of GC patients." (PMID 29970131, 2018). "The mean tumour size and tumor weight in sh-UFC1 group were remarkably lower than that in control group." (PMID 29970131, 2018). "The expression of linc-UFC1 was significantly elevated in the CRC tissues compared with the adjacent non-tumor tissues (P<0.01)." (PMID 27195675, 2016). "Examination of the correlations between linc-UFC1 expression and clinical pathological features showed that the upregulation of linc-UFC1 was correlated with the tumor histology grade, N grade and M grade." (PMID 27195675, 2016). "Therefore, our results support that ANRIL and/or UFC1 is an attractive target for drug development in tumor growth and aggressive proliferation of NSCLC, and that a valuable outcome can be achieved through the miRNA-34a/Myc pathway." (PMID 35327612, 2022). "Therefore, our results support the idea that ANRIL and/or UFC1 is an attractive target of drug development in tumor growth and the aggressive proliferation of NSCLC, and that a reasonable outcome can be achieved through the miRNA-34a/Myc pathway." (PMID 35327612, 2022). "ANRIL and UFC1 are up-regulated and play a crucial role in tumor progression in NSCLC." (PMID 35327612, 2022). "UFC1 bound to miR-498 to antagonize its tumor suppressive effect on Lin28b." (PMID 29970131, 2018). "UFC1 acted as a ceRNA for Lin28b oncogene by sponging tumor-suppressive miR-498." (PMID 29970131, 2018).
tumor (continued). "However, the mean tumor size and tumor weight in Lin28b co-transfection group were remarkably higher than that in sh-UFC1 alone group." (PMID 29970131, 2018). "Moreover, positive correlations between linc-UFC1 expression and clinical parameters, including tumor grade, N stage and M stage, were detected." (PMID 27195675, 2016). "Moreover, there was a negative association between the expression level of UFC1 and that of miR-498 in tumor tissues (r = − 0.52, P < 0.001)." (PMID 29970131, 2018). "Long non-coding RNA (LncRNA) UFC1 is upregulated in serum exosomes, tumor tissues, and serum of patients with NSCLC, and shows a positive correlation with tumor infiltration." (PMID 41573685, 2025). "Further bioinformatics analysis of miR-24-1-5p targets, including CD34, ACACA, TPM3, UFC1, EDIL3, and CHEK1, reinforces their role in tumor immune cell infiltration and the transformation of the tumor microenvironment." (PMID 38840234, 2024). "In tumour tissues, serum and serum exosomes of NSCLC patients, UFC1 was overexpressed concomitant with tumour infiltration." (PMID 33669294, 2021). "In conclusion, our present study showed that UFC1 was upregulated in NSCLC cells and tumor tissues, serum and serum exosomes of NSCLC patients." (PMID 32242003, 2020). "Increased UFC1 expression levels in NSCLC tissues were positively correlated with age (P = 0.03) and tumor infiltration (P = 0.02)." (PMID 32242003, 2020). "In this study, linc-UFC1 was overexpressed in CRC patient tissues and positively correlated with tumor grade, N stage and M stage." (PMID 27195675, 2016). "Recently, tumor-promoting roles of lncRNA ANRIL and lncRNA UFC1 were reported in NSCLC." (PMID 35740511, 2022). "Moreover, correlation analysis using 27 paired NSCLC tissues and adjacent normal tissues showed that there was a negative association between the expression of UFC1 and that of PTEN in tumor tissues (r = −0.518, P < 0.05)." (PMID 32242003, 2020). "However, linc-UFC1 expression was not correlated with patients' gender, age, tumor size or T grade." (PMID 27195675, 2016).
cancer (13 papers, 2016 to 2025). A tumor composed of atypical neoplastic, often pleomorphic cells that invade other tissues. "Lately, many studies have postulated that targeting ANRIL and/or UFC1 can regulate cancer proliferation through the enhanced expression of miR-34a." (PMID 35327612, 2022). "They found that UFC1 targets PTEN through the induction of EZH2 while the knockdown (KO) of UFC1 inhibits cancer proliferation and induces apoptosis and cell-cycle arrest." (PMID 35327612, 2022). "In contrast, miR-34a is a negative regulator of UFC1 and thus prevents the induction of β-catenin in cancer cells." (PMID 35884580, 2022). "Of note is that the expression of long non-coding RNA (lncRNA) and long intergenic RNA (lincRNA) for UFC1 regulates the progression of numerous cancer types including gastric, breast, pancreatic and colorectal cancers through modulation of specific micro-RNAs." (PMID 33578803, 2021). "In this study, flow cytometry analysis and an EdU incorporation assay demonstrated that linc-UFC1 downregulation induced cell cycle arrest at the G1 phase and lowered the percentage of cancer cells in S phase." (PMID 27195675, 2016). "We knocked down linc-UFC1 in LOVO and SW480 cancer cells by transfecting the cells with short hairpin RNAs (shRNAs), sh-linc-UFC1." (PMID 27195675, 2016). "The lncRNA UFC1 has been known as an oncogenic lncRNA regulating EZH2 signaling in cancer." (PMID 34439315, 2021). "In summary, these data suggest that NSCLC cells derived exosomes may transmit UFC1 to promote cancer progression by downregulating PTEN." (PMID 32242003, 2020). "Amplification, deletion or mutation of genes encoding the UFMylation factors (UBA5, UFC1, UFL1, UfSP2 and UFM1) has been detected in malignant tumors from various tissues and organs in the TCGA database, indicating that UFMylation may promote or suppress tumorigenesis in different cellular contexts." (PMID 30783677, 2019). "A comprehensive analysis of genomic alterations in the eight UFMylation family genes (UFM1, UBA5, UFC1, UFL1, UfBP1, CDK5RAP3, UfSP1, and UfSP2) across the TCGA database of 33 cancer types identified 55 recurrent and focal somatic copy number alteration events in UFMylation family genes." (PMID 37947621, 2023). "Herein, we reported another lncRNA UFC1 that could regulate PTEN expression at the epigenetic level, which adds more information for the regulatory network of PTEN in cancer." (PMID 32242003, 2020). "In this study, we investigated linc-UFC1 expression in CRC tissues and cancer cell lines." (PMID 27195675, 2016).
neurological diseases (2 papers, 2024 to 2025). "Hesperetin, a citrus flavonoid known for its neuroprotective effects in neurological diseases, was tested for its potential positive effects in cells harboring mutated UFC1." (PMID 39846712, 2025). "UFC1 is involved in ubiquitination as an E2 conjugating enzyme and interacts with neuronal cell adhesion molecules in neurological diseases." (PMID 39610716, 2024).
UFC1 also shares sentences with these, for which no sentence is quoted: developmental delay (3 papers); neurodevelopmental disorder (3); breast carcinoma (2); atherosclerosis (1); bladder cancer (1); diabetes (1); Epileptic encephalopathy (1); Failure to thrive (1); fibrosis (1); Hip dysplasia (1); ischemic heart diseases (1); myeloid leukemia (1); Onset (1); pancreatic adenocarcinoma (1); prostate carcinoma (1); schizophrenia (1); spinocerebellar ataxia (1).